VRTN (vertebrae development associated)
Description:
Acts as a transcription factor that regulates development of thoracic vertebrae.
Synonyms: C14orf115; FLJ10811; vertnin
Tractability: No criterion of Open Targets' tractability assessment is met for any kind of drug.
Gene: Protein-coding gene on chromosome 14 (74,303,069 to 74,360,011, forward strand). Ensembl gene ENSG00000133980.
Subcellular location: Nucleus
Subcellular location (Human Protein Atlas): Nucleoplasm
Gene Ontology:
Molecular function: protein binding; sequence-specific DNA binding
Biological process: regulation of transcription by RNA polymerase II
Cellular component: chromatin; nucleus
Genetic constraint (gnomAD): Loss-of-function variants: 5 observed, 19.61 expected, observed/expected ratio (o/e) 0.25, 90% interval 0.13 to 0.54. The upper end of that interval is the gene's LOEUF score, 0.54, which puts it in group 2 of 6, group 1 being the genes least tolerant of losing a copy. Missense variants: 741 observed, 967.68 expected, observed/expected ratio (o/e) 0.77, 90% interval 0.72 to 0.81. Synonymous variants: 381 observed, 406.02 expected, observed/expected ratio (o/e) 0.94, 90% interval 0.86 to 1.02.
Homologues: Orthologues: chimpanzee VRTN (99% identical), macaque VRTN (96% identical), pig VRTN (86% identical), rabbit VRTN (82% identical), guinea pig VRTN (81% identical), dog VRTN (81% identical), rat Vrtn (75% identical), mouse Vrtn (74% identical), zebrafish vrtn (41% identical).
Diseases named in the same sentence as VRTN in open-access papers:
VRTN is named in the same sentence as 10 diseases in open-access papers, as found by Europe PMC text mining. Sharing a sentence is not in itself a finding about the gene and the disease. The quoted sentences say what the papers report.
asthma (1 paper, 2025). "Participants with the VRTN rs138257884 variant are more likely to develop K13 disorders of the lip and oral mucosa (OR: 7.80, p = 0.0068), J43 emphysema (OR: 7.64, p = 0.025), and J45 asthma (OR: 3.04, p = 0.029)." (PMID 41261143, 2025).
Huntington disease (1 paper, 2013). Huntington disease (HD) is a rare neurodegenerative disorder of the central nervous system characterized by unwanted choreatic movements, behavioral and psychiatric disturbances and dementia. "Of them, SYNDIG1L seem to be implicated in Huntington diseases in rodent models, while VRTN has been proposed as a strong candidate of the QTL for vertebral number." (PMID 23638110, 2013).
VRTN also shares sentences with these, for which no sentence is quoted: congenital heart disease (1 paper); diabetes (1); emphysema (1); head and neck squamous cell carcinoma (1); invasive breast carcinoma (1); kidney diseases (1); Obesity (1); tumor (1).